BRAF (B-Raf proto-oncogene, serine/threonine kinase)
Diseases named in the same sentence as BRAF in open-access papers (continued):
Sharing a sentence is not in itself a finding about the gene and the disease.
papillary thyroid carcinoma (continued). "Specific genetic variants of LGALS3 influence the risk of developing TC, and its role in the invasiveness of BRAF-mutated papillary thyroid carcinoma highlights its potential as a therapeutic target in tumor progression." (PMID 39928612, 2025). "Of the two nodules with the BRAF V600E mutation, one was diagnosed as papillary thyroid carcinoma (PTC) and classified in the Bethesda IV category, while the second nodule (Bethesda III) is still awaiting surgery." (PMID 40748901, 2025). "Adequate DNA for molecular testing was obtained in 30 of 33 cases (90%), and BRAF V600E mutations were detected in three papillary thyroid carcinoma samples." (PMID 41303583, 2025). "The BRAF V600E mutation, frequently found in papillary thyroid carcinoma, is a useful molecular marker for diagnosis, risk stratification, and potential targeted therapy." (PMID 40746588, 2025). "In previous studies, the prevalence of BRAF V600E mutation was 40%–50% in Caucasian papillary thyroid carcinoma (PTC) patients, and ranged from 72%–81% in Asian PTC patients." (PMID 40395668, 2025). "The BRAF V600E mutation in papillary thyroid carcinoma (PTC) is linked to aggressive behavior and frequent occult central lymph node metastases (CLNM), posing a surgical dilemma in clinically node-negative (cN0) patients." (PMID 41458539, 2025). "BRAF V600E mutations were detected in both left pleural metastatic lesions of papillary thyroid carcinoma and the primary tumour of NSCLC." (PMID 39950095, 2025). "The additional mutation analysis of the left pleural metastatic lesion of papillary thyroid carcinoma also detected BRAF V600E mutation by Oncomine DxTT." (PMID 39950095, 2025). "The calibration curve closely followed the ideal curve, which indicates high calibration accuracy and confirms the model’s strong potential for predicting BRAF gene mutation in papillary thyroid carcinoma (PTC)." (PMID 41199838, 2025). "BRAF V600E mutation, which occurs in 50% of well-differentiated papillary thyroid carcinomas, are detected in 25–30% of ATC." (PMID 40214777, 2025). "BRAF V600E is the most common early driver in differentiated thyroid cancer, and 50% of ATC cases have a history or are associated with DTC, hence 10% to 50% of ATC cases harbor this mutation." (PMID 40485736, 2025). "Genetic molecular testing detected the BRAF V600E mutation via quantitative polymerase chain reaction assay, raising concern for papillary thyroid cancer (PTC)." (PMID 39288226, 2024). "The BRAF V600E mutation, with its relatively high prevalence and specificity in papillary thyroid carcinoma (PTC), holds particular significance, especially in East Asian populations." (PMID 39568807, 2024). "were the first to report that BRAF mutations were confined to patients with papillary thyroid carcinoma (PTC) or to those with poorly differentiated or anaplastic thyroid cancers arising from previous PTC." (PMID 39529955, 2024). "BRAF mutations occur in approximately 55% of all papillary thyroid carcinomas, and specifically the BRAF V600E mutation is the most common genomic alteration." (PMID 38616265, 2024). "In comparison, BRAF p.V600E occurs in over 50% of adult papillary thyroid carcinoma (PTC) and NRAS/HRAS/KRAS mutations in 30-45% of follicular thyroid cancer and follicular variant PTC." (PMID 39558957, 2024). "The BRAF V600E mutation is enriched in the conventional papillary thyroid cancer subtype, driving a more aggressive phenotype with higher risk of recurrence than patients without the mutation." (PMID 38304083, 2024). "For patients with the BRAF V600E mutation, the mortality risk significantly increases with each additional year of age, with HR values ranging from 1.03 in papillary thyroid carcinoma (PTC) to 1.05 in medullary thyroid carcinoma (MTC)." (PMID 39767732, 2024).
papillary thyroid carcinoma (continued). "Further, in a BRAF-mutated papillary thyroid cancer cell line (BCPAP), vemurafenib, an inhibitor of mutant BRAF activity, was shown to upregulate VCAM-1 expression, which was reduced by the administration of the Akt inhibitor MK2206." (PMID 39768198, 2024). "Preoperative thyroid puncture identified papillary thyroid carcinoma, and genetic testing revealed a BRAF gene exon 15-point mutation." (PMID 38941410, 2024). "Aggressive variants of papillary thyroid carcinoma (e.g., tall cell, diffuse sclerosing, and hobnail) and mutations such as BRAF V600E and TERT promoter are also associated with increased tumor aggressiveness and RAI-R disease." (PMID 39685478, 2024). "The BRAF mutation is a common genetic alteration observed in papillary thyroid carcinoma and plays a significant role in disease progression and survival rates." (PMID 39767732, 2024). "Our analysis focused on papillary thyroid carcinomas (PTCs) samples with two risk factors: BRAF mutation status (a categorical risk factor) and age of diagnosis (a continuous risk factor)." (PMID 39677786, 2024). "Another study looking at 16 patients with small papillary carcinomas and their lymph node metastases found BRAF V600E mutation in 75% of tumors, but a low mutational burden in both lymph node metastases and primary tumors." (PMID 38616265, 2024). "Particularly for papillary thyroid cancer, we identified the prevalence of BRAF V600E mutations in 68.4% of the samples, which was at the high end of the reported range (32%–65%)." (PMID 38404964, 2024). "Approximately 90% (321/356) of the AUS nodules were malignant, predominantly papillary thyroid carcinoma with 68.6% BRAF V600E mutations." (PMID 39568807, 2024). "BRAF mutations are present in approximately 50% of papillary thyroid cancers (PTC) and are strongly associated with the inhibition of NIS expression and the development of RAI-R disease." (PMID 39685478, 2024). "v.BRAF p.V600E mutation or equivalent molecular alterations (BRAF p.V600E-like tumors) are “Early/Driver” events (see paragraph (ii)) for conventional papillary carcinoma." (PMID 38108848, 2024). "In BRAF-mutated papillary thyroid carcinomas, senescent tumor cells promote the collective invasion of senescent and non-senescent tumor cells via their SASP." (PMID 36980745, 2023). "She underwent bilateral thyroid nodule fine-needle aspiration biopsy and BRAF gene testing at our hospital, with results indicating bilateral papillary thyroid carcinoma and positive BRAF gene V600E mutation." (PMID 37869421, 2023). "The most common mutation found in papillary thyroid carcinoma cases is the V600E mutation found in the BRAF gene, yet these patients have a relatively low probability of cancer recurrence." (PMID 38115146, 2023). "This study aimed to investigate the relationship between the allele frequency (AF) of the BRAF V600E mutation and the histopathological features of papillary thyroid cancer (PTC), with a focus on its aggressive behavior." (PMID 38201541, 2023). "Patients with papillary thyroid carcinoma who have the BRAF mutation frequently experience metastases and relapses of the disease after the cancer has progressed aggressively." (PMID 38115146, 2023). "The BRAF p.V600E mutation represents the most specific marker for papillary thyroid carcinoma and is potentially related to aggressive behavior and persistent disease." (PMID 36835466, 2023). "Histology showed an anaplastic thyroid carcinoma (TNM: pT4b Nx M1; V1; stage IVc) and components of a papillary thyroid carcinoma with a positive BRAF-mutation (c.1799 T > A; p.V600E)." (PMID 36855200, 2023). "In BRAF-mutated papillary thyroid cancer and differentiated thyroid cancer, a similar mechanism did not impact the clinical efficacy." (PMID 37059834, 2023). "BRAF mutation is one of the most common genetic alterations contributing to the initiation and progression of papillary thyroid carcinoma (PTC)." (PMID 36843593, 2023).
papillary thyroid carcinoma (continued). "detected mutations in the BRAF gene in a specimen associated with a patient with high cellular variant (TCV) papillary carcinoma that exhibited squamous transformation years later." (PMID 38303977, 2023). "BRAF mutations are found in 60–80% of papillary thyroid carcinomas (PTC), and the most frequent alteration is the BRAF p.V600E." (PMID 36835466, 2023). "A recent work analyzing the concomitant factors BRAF mutation (risk factor) and Hashimoto’s thyroiditis (HT) (protective factor) found that the presence of HT reduced lymph node metastasis in BRAF-mutated papillary thyroid carcinoma." (PMID 37190300, 2023). "In papillary thyroid carcinoma driven by BRAF pathway mutations, there is decreased expression of sodium iodide symporter (NIS), TSH receptors and tumor cell specific MHC II." (PMID 38136348, 2023). "Follicular variant papillary thyroid carcinoma (FV-PTC) was the most common histological subtype harboring BRAF non-V600E mutations (8 of 19 cases, 42.1%)." (PMID 36835466, 2023). "Mutations in the BRAF-V600E gene occur in approximately 45% of papillary thyroid cancers, while mutations in the RAS and ALK genes are frequently found These mutations drive mTOR pathway activation and lead to thyroid tumourigenesis." (PMID 37773165, 2023). "In adults, various RET/PTC rearrangements have also been described as the predominant driver mutation in radiation-induced papillary thyroid cancer, while BRAF V600E mutations are more common in sporadic papillary thyroid cancer." (PMID 37190143, 2023). "Dual modulation of the MAPK pathway with BRAF (e.g., dabrafenib) and MEK (e.g., trametinib) inhibitors has the potential to re-establish radioiodine (RAI) sensitivity in BRAF-mutated RAI-refractory (RAI-R)-differentiated thyroid carcinoma (DTC) cells." (PMID 37191938, 2023). "BRAF mutations are the most common mutations in papillary thyroid cancer (PTC) patients, occurring in up to 45%." (PMID 36060256, 2022). "The study of genetic mutations reveals a positivity of 50–55% for the BRAF mutation in papillary carcinomas and 33.3% in follicular carcinomas." (PMID 35260614, 2022). "BRAF-V600E mutations were found in papillary thyroid carcinomas in 40.3% patients with mean age of 53 years old." (PMID 36510281, 2022). "All five nodules harbouring the BRAF V600E mutation were malignant carcinomas, including three classic papillary thyroid carcinomas, one follicular variant papillary carcinoma and one anaplastic thyroid carcinoma concurrent with TERT mutation." (PMID 35247035, 2022). "Even though it is considered as malignancy with good prognosis, recent study with 15-year median follow up showed significantly lower survival percentage in papillary thyroid carcinoma with BRAF mutation." (PMID 36510281, 2022). "BRAF-V600E mutation is common in patients with papillary thyroid carcinoma (PTC) and has been associated with an aggressive phenotype." (PMID 35332119, 2022). "Cluster 5 was concerned about BRAF (V600E), which accounts for 60-80% of papillary thyroid carcinoma (PTC) and is a prognostic marker for risk stratification in PTC patients." (PMID 36004350, 2022). "For example, this has been done in the study of papillary thyroid carcinoma, a type of cancer with significant BRAF V600E mutation." (PMID 36428683, 2022). "Since the prognostic value of BRAF mutations remains controversial, this study aims to investigate the importance of this mutation in therapeutic decisions for papillary thyroid carcinoma." (PMID 32972866, 2022). "BRAF mutation accounts for 50% of the PTC (papillary thyroid carcinoma) and is closely associated with high-risk clinicopathological characteristics." (PMID 35651980, 2022). "Point mutations in the RAS or BRAF proto-oncogenes were detected in almost 70% of papillary thyroid carcinomas in nearly mutually exclusive manner." (PMID 36510281, 2022).
papillary thyroid carcinoma (continued). "BRAF exon 15 p.V600E (BRAF V600E) mutation has been established as an important molecular marker for papillary thyroid carcinoma diagnosis by ultrasound-guided fine-needle aspiration biopsy (FNAB)." (PMID 35392249, 2022). "Relationship between BRAF mutations and US imaging characteristics through visual assessment of papillary thyroid carcinomas." (PMID 35527993, 2022). "The BRAF V600E mutation in THCA was mainly distributed in papillary thyroid cancer (PTC) and anaplastic thyroid carcinoma (ATC)." (PMID 35910024, 2022). "In differentiated thyroid cancer, the most common genetic changes include BRAF and RAS mutations and RET rearrangement." (PMID 34986823, 2022). "BRAF-mutated, poorly differentiated, anaplastic carcinoma will have a papillary component, suggesting that these tumors progress from BRAF-positive papillary carcinoma." (PMID 34345541, 2021). "This study focuses on the oncologic influence of BRAF V600E mutations in a cohort of Middle Eastern papillary thyroid carcinoma (PTC) patients treated at a single centre." (PMID 34734568, 2021). "More than a half of papillary thyroid cancers are driven by BRAF mutations affecting codon 600; these tumors are sensitive to the inhibitors of mutated BRAF." (PMID 34681592, 2021). "Papillary thyroid cancer is mainly reported to be associated with the missense mutation of B-raf proto-oncogene (BRAF, serine/threonine kinase) and rearrangement of RET/PTC1, RET/PTC3, and neurotrophic tyrosine kinase-1/3 (NTRK1/3) genes." (PMID 33805984, 2021). "In the thyroid, apart from papillary carcinomas, BRAF mutations are expressed in anaplastic carcinoma and poorly differentiated carcinoma (prevalence, 20%-30%, and 10%-15%, respectively)." (PMID 34345541, 2021). "This is the first case of solitary brain metastasis of occult papillary thyroid carcinoma with double mutation of BRAF L597Q and V600E in 2 separate lesions reported in the literature." (PMID 33578538, 2021). "This approach was trained using papillary thyroid carcinoma cases to predict BRAF V600E mutation status, achieving a reported AUC of 0.88." (PMID 34441338, 2021). "BRAF mutations occur early and play an important role in the pathogenesis of papillary thyroid carcinoma (PTC)." (PMID 34345541, 2021). "Another parameter likely contributing to the heterogeneity of BRAF rates was regional variations in the prevalence of BRAF mutation and/or papillary thyroid carcinoma." (PMID 33052631, 2021). "Nonetheless, controversies regarding BRAF mutations with poorer clinicopathological outcomes in papillary thyroid cancers have been reported in some studies." (PMID 34345541, 2021). "We present the first rare case of occult papillary thyroid carcinoma with BRAF L597Q mutation in a Tibetan patient." (PMID 33578538, 2021). "They suggest the potential therapeutic role of COX-2 inhibition in patients with BRAF-mutated papillary thyroid carcinoma." (PMID 34199169, 2021). "We tested the association of BRAF V600E mutation with papillary thyroid carcinoma at King Hussein Cancer Center." (PMID 34734568, 2021). "In contrast, decreased expression of ERRFI1 is associated with a more aggressive phenotype of papillary thyroid cancer with BRAF mutation." (PMID 34206547, 2021). "BRAF V600E mutation-positive papillary thyroid carcinomas consistently showed all characteristic nuclear features, such as nuclear crowding, overlapping, and grooves." (PMID 34345541, 2021). "In this respect, the connection between methylation of the MLH1 gene and lymph node metastasis in patients with papillary thyroid carcinoma with T1799A BRAF mutation has been reported as epigenetic differentiation of MLH112." (PMID 33976347, 2021). "According to data from exome and whole genome sequencing of 496 papillary thyroid carcinomas from the TCGA project, BRAF somatic mutations were identified in 246 (62%) of 399analysed patients." (PMID 34070605, 2021).
papillary thyroid carcinoma (continued). "A study shows that COX-2 plays a key role in prognosis of Middle Eastern papillary thyroid carcinoma patients, especially in BRAF-mutated tumors." (PMID 34199169, 2021). "BRAF mutation has been associated as a poor prognostic factor in other cancer types, for example in papillary thyroid cancer." (PMID 34537078, 2021). "Among 47 identified cases, 14 were positive for the BRAF V600E mutation and had papillary carcinoma (n = 9) or follicular neoplasms (n = 5; follicular adenoma, n = 3; follicular carcinoma, n = 2)." (PMID 34345541, 2021). "The BRAF-V600E point mutation is the most common genetic mutation detected in patients with papillary thyroid cancer (PTC) and occurs in approximately 45–60% of patients." (PMID 34319022, 2021). "In turn, there is information about the protective effect of the BRAF-V600E mutation and a decrease in the likelihood of lung damage in papillary thyroid cancer." (PMID 34319022, 2021). "BRAF mutations have been significantly associated with capsule in papillary thyroid carcinomas, and BRAF signaling plays a critical role in regulating HCC cell proliferation." (PMID 34007838, 2021). "Individual statistical validation of HBME-1, galectin-3 expression, and BRAF V600E mutation in differentiating among papillary thyroid carcinoma, papillary thyroid hyperplasia, follicular adenoma, and follicular carcinoma." (PMID 34934597, 2021). "The data above suggest that the point mutation BRAF V600E possibly plays a pathognomonic role in papillary thyroid cancer." (PMID 34630336, 2021). "In thyroid neoplastic pathology, the BRAF V600E mutation is shown to be involved in the oncogenesis of papillary thyroid cancer (PTC) and its subtypes." (PMID 32575591, 2020). "Aberrant methylation was demonstrated in the HOXD10 promoter in papillary thyroid cancer (PTC) tissues with concomitant BRAF V600E mutation." (PMID 33198372, 2020). "Many papillary thyroid cancers possess a mutated BRAF gene, most commonly the point mutation T1799A or BRAFV600E, which activates the MAPK pathway causing a loss of control of cellular proliferation, triggering the oncogenesis of thyroid gland." (PMID 32357861, 2020). "BRAF p.V600A is a RAS-like BRAF exon 15 mutation according to the Cancer Genome Atlas classification of papillary thyroid carcinoma and is compatible with the diagnosis of encapsulated follicular variant papillary carcinoma." (PMID 32059434, 2020). "In papillary thyroid carcinoma, patients with BRAF expression were associated with older age and higher tumor recurrence rates than patients without BRAF expression." (PMID 32961530, 2020). "BRAF exon 15 mutations are the most common molecular alterations found in papillary thyroid carcinoma (PTC)." (PMID 32059434, 2020). "In thyroid neoplastic pathology, the BRAF V600E mutation is shown to be involved in the oncogenesis of papillary thyroid cancer and its subtypes." (PMID 32575591, 2020). "Previous meta-analyses indicated that the BRAF V600E mutation was associated with an increased recurrence rate of papillary thyroid carcinoma (PTC)." (PMID 32722429, 2020). "Mutation in the BRAF gene is the most common abnormality in adult papillary thyroid carcinoma, but is very rare in children." (PMID 32357198, 2020). "The BRAF-V600E mutation is the most common and specific oncogenic event known in papillary thyroid carcinoma (PTC)." (PMID 31897179, 2020). "An in-frame fusion of the AKAP9 gene (exons 1–8) to the BRAF gene (exons 9–18), which occurs through a paracentric inversion of chromosome 7, has been preferentially recognised in radiation-induced papillary carcinomas, compared with BRAF point mutations." (PMID 31762942, 2019). "Another Phase I study evaluated the ability of Trametinib to induce re-differentiation of radioiodine-refractory BRAF V600E-mutated papillary thyroid carcinoma." (PMID 31762942, 2019).